PLK1 (polo like kinase 1)
Diseases named in the same sentence as PLK1 in open-access papers (continued):
Sharing a sentence is not in itself a finding about the gene and the disease.
tumor (continued). "PLK1 may exert an influence on the immune microenvironment and impact anti-tumor immune responses." (PMID 37744268, 2023). "Therefore, the downregulation of this RI might be a key factor leading to the aberrant expression of the dominant PLK1 isoform (PLK1‐201) by splicing PLK1‐N1 to PLK1‐201, thereby affecting tumor progression." (PMID 36461702, 2023). "Notably, there was a higher abundance of tumor-promoting immune cells, such as Type 2 T helper cells, Myeloid-derived suppressor cells (MDSCs) and regulatory T cells, in the PLK1-high groups, which may be responsible for the worse prognosis." (PMID 38186570, 2023). "Thus, by designing sgRNAs targeting PLK‐1, the anti‐tumor activity of this system can be explored." (PMID 36925702, 2023). "The results revealed the high expression of AURKB, CCNA2, and PLK1 in tumor tissues when compared to normal tissues and we also found that there was a strong positive correlation with the DNA replication, G2M checkpoint, and tumor proliferation signature pathways." (PMID 37238607, 2023). "Furthermore, we observed that cells with forced expression of ST8SIA6-AS1 exhibited similar sensitivity to Volasertib or MYCi975 treatment compared to control cells, indicating that PLK1/c-Myc function largely mediated the tumor-promoting effect of ST8SIA6-AS1." (PMID 38104151, 2023). "Indeed, we observed opposite expression patterns of PLK1‐N1 and PLK1‐201 in tumor and tumor‐adjacent tissues, which provided further support to our hypothesis." (PMID 36461702, 2023). "The complement factor H-related (CFHR) protein family induces the ubiquitination of polo-like kinase 1 (PLK1) at lysine 209, BRCA1-associated protein 1 (BAP1) enhances genomic stability, and USP9X is found to restrain tumor growth in the patient-derived tumor xenograft (PDX) model." (PMID 38174069, 2023). "Therefore, PLK1 might be highly expressed in other cells in the tumor microenvironment, implicating the role of the local microenvironment in tumorigenesis." (PMID 36618405, 2022). "In addition, we found that the expressions of AURKA, CCNA2, CCNE1, CDK1, CHEK1, and PLK1 were all positively correlated with TMB, which was consistent with previous research results, and there was a positive correlation between tumor dryness and tumor mutation burden." (PMID 36483630, 2022). "Furthermore, analysis of a mouse model of pancreatic carcinogenesis that overexpresses METTL3 indicates that the upregulated effect of cell cycle by METTL3 is tumor cell-specific and that the antitumor effect of PLK1 inhibition is stronger in tumor cells compared with normal pancreatic duct cell." (PMID 35773310, 2022). "Thus, ideal drug delivery system (DDS) that exhibit affinity for CAFs and tumor cells might hold potential for sequentially delivering PLK1 inhibitor (Ro3280)." (PMID 35664077, 2022). "In addition, PLK1 may be a tumor recognition antigen for T lymphocytes, which has important implications in tumor immunotherapy." (PMID 35256538, 2022). "Our finding of PLK1 inhibitor being effective in inhibition of ACHN OIP5 tumor growth may have significant clinical applications in treating metastatic pRCC with OIP5 upregulation; this will offer a venue for potential utilization of personalized therapy in pRCC." (PMID 34503297, 2021). "Hence, Plk1 appears as a central player facilitating tumor development and progression." (PMID 33547392, 2021). "The aptamer-targeted nanoparticles could efficiently deliver cargoes into MDA-MB-231 breast tumor with overexpressed nucleolin receptors, and folate-decorated nanoparticles delivering RNP targeting Plk1 exhibited significant gene disruption and tumor growth inhibition in vivo." (PMID 33391496, 2021). "However, in some tumor types high‐level PLK1 expression can suppress cancerogenesis." (PMID 34605140, 2021). "Therefore, the elevated anti-tumor immunological effect might be partially attributed to the relief of immunosuppressive effects after targeting PLK1." (PMID 34522178, 2021).
tumor (continued). "In the light of highly proliferating tumor cells and the cell cycle-dependent expression of the mitotic kinase, high expression of PLK1 may not be a cause but a consequence during tumorigenesis just reflecting high mitotic rate." (PMID 34065956, 2021). "Thus, the increased Cdk1 and Plk1 expression in MmuPV1-induced tumor tissues may promote the expression and phosphorylation of CtIP." (PMID 34343212, 2021). "Moreover, PLK1 could be used as an independent prognostic factor for tumor recurrence in CRC according to univariate and multivariate analyses." (PMID 34881526, 2021). "In addition, PLK1 inhibitors volasertib and onvansertib were cytotoxic at low nanomolar concentrations in all the mEOC cell lines tested, similarly to what has been reported in other tumor cells." (PMID 32183025, 2020). "Furthermore, immunoblotting assay also showed that the protein levels of MELK, phospho-FOXM1 (T600), and its downstream targets (PLK1, Cyclin B1 and Aurora B) were much higher in tumor cell lysates derived from MELK-overexpressing mice than those from the control group." (PMID 32047721, 2020). "In particular the authors focused on Plk1, which expression is elevated in tumor cells, showing that the delivery of siPlk1 through the nanovesicle was facilitated activating apoptotic pathways and inhibiting tumor cell growth as a result of the gene silencing." (PMID 33212974, 2020). "However, in normal cells, lowly expressed c-Myc accompanies with low levels of SKA3 and PLK1, indicating that the SKA3–PLK1–AKT axis may represent tumor-specific characteristics." (PMID 33106477, 2020). "We observed whether the expression of active PLK1 enhanced metastasis and tumor formation." (PMID 31548612, 2020). "Dysfunction of PLK1 may promote cancerous transformation and drive tumor progression." (PMID 33352742, 2020). "Therefore, in in vivo transfection, PEG-modification of LP-HAPC with more PEG2000-DSPE might be needed for suppression of the anti-tumor effect by PEG-modified lipoplexes with PLK1 siRNA." (PMID 30991703, 2019). "However, in in vivo transfection, both LP-HAPC-2mol%PEG2000 and LP-HAPC-2mol%FA-PEG2000 lipoplexes with PLK1 siRNA inhibited tumor growth compared with Cont siRNA, indicating that the in vivo anti-tumor effect of PEG-modified siRNA lipoplexes was not correlated with the in vitro one." (PMID 30991703, 2019). "The finding that the combination of Plk1 and cMet inhibition led to striking tumor regression in vivo in both epithelial and mesenchymal NSCLC suggests that this combination would be broadly effective in NSCLC patients who may have tumors with heterogeneity or dynamic changes in EMT status." (PMID 31040125, 2019). "However, Plk1-overexpressing tissues were characterized by the presence of cells with higher nuclear volume as well as increased apoptotic cell death with independence of Kras status at these early time points, likely contributing to reduced tumor burden in the presence of elevated Plk1 levels." (PMID 30069007, 2018). "Indeed, 50% of Her2/Plk1 tumor cells displayed mitotic errors compared to 24% of Her2 alone." (PMID 30069007, 2018). "Moreover, inhibition of PLK1 by BI6727 suppressed the tumor-sphere formation of ATRT cells." (PMID 29228610, 2017). "Finally, selective DNA damage induction by HDACIs and high expression of PLK1 in tumor cells suggests that combinations might preferentially target neoplastic cells." (PMID 28416758, 2017).
tumor (continued). "Hence, an in-depth comprehension of the molecular mechanism of PLK1 in tumor metastasis and inferior prognosis may pave the way toward new prognostic models." (PMID 29190933, 2017). "Also, FBXW7, MCL1 and PLK1 may be relevant predictive markers of tumor progression and response to paclitaxel treatment." (PMID 27409838, 2016). "Since senescence could promote tumor development and contribute to therapy resistance, the senescence induction upon Plk1 inhibition in tumor and normal cells could contribute to the moderate efficacy observed in patients treated with Plk1 inhibitors." (PMID 27713178, 2016). "Interestingly, PLK1 expression was related to histological grading of tumor and capsule invasion." (PMID 25019081, 2014). "Therefore, it was concluded that miR-100 may function as a tumor suppressor in EOC by targeting PLK1." (PMID 22246341, 2012). "Moreover, on day 70 after the inoculation of tumor cells, livers of mice treated with nonsense siRNA/atelocollagen or PBS/atelocollagen complex had numerous large tumor nodules, whereas the livers of mice treated with PLK-1 siRNA/atelocollagen complex showed a much lower number of smaller nodules." (PMID 21884621, 2011). "Therefore, understanding the mechanism of adaptation in yeast may provide valuable insight into the role of PLK1 overexpression in tumor progression." (PMID 20126259, 2010). "Thus, Plk1 can also be considered as a "haploinsufficient tumor repressor"." (PMID 19161615, 2009). "However, in a recent study, it has been suggested that down-regulation of Plk1 could also induce aneuploidy and tumor formation in vivo." (PMID 19161615, 2009). "Accordingly, our previous study showed that the PLK1/c-Myc pathway mediates resistance to KRASG12C inhibitors in NSCLC, and co-inhibition of PLK1 and KRASG12C synergistically suppresses tumor growth and overcomes this resistance." (PMID 41539998, 2026). "Considering the established link between EMT, tumor metastasis, and poor prognosis in EGFR-mutant NSCLC, we investigated the effects of PLK1 inhibitors combined with osimertinib on the migratory properties of resistant cells." (PMID 41539998, 2026). "In the genomic analysis of LUAD, the levels of TNFAIP6 were higher in patients with advanced stages 2-4 (75%) than in those with tumor stage 1 (66%), indicating that TNFAIP6 and PLK1 were markedly expressed in advanced LUAD." (PMID 40860188, 2025). "Targeting PLK1 significantly inhibits cell proliferation, triggers cell cycle arrest, induces DNA damage and apoptosis in EOC cells, and suppresses tumor growth while prolonging survival in animal models of EOC." (PMID 41458961, 2025). "We previously demonstrated that changes in the expression of PLK1 and other genes that regulate CIN, along with factors that remodel the tumor microenvironment, represent some of the earliest events in tumor evolution." (PMID 40347943, 2025). "Therapeutically, suppression of PLK1 by this inhibitor attenuated NSCLC tumor growth and sensitized tumors to cisplatin in allograft tumor models." (PMID 40355412, 2025). "The expression levels of TFRC, LAMC1, PLK1, TYMS, and TSSK6 were significantly higher in tumor tissues while TNFSF14 exhibited higher expression levels in normal tissues." (PMID 40496862, 2025). "PLK1 was detected in 38% of B4-treated A549/DDP tumor tissues, while this value decreased to 20% in tumor tissues treated with B4 and cisplatin." (PMID 40355412, 2025). "In summary, we revealed that USP10, as a tumor promoter, promoted the progression and attenuated GEM chemotherapy sensitivity via stabilizing PLK1 in PDAC, providing a potential target for the treatment of PDAC." (PMID 40517136, 2025).
tumor (continued). "MiR-149-3p reduces polo-like kinase 1 (PLK1) expression, a crucial regulator of cell cycle progression and apoptosis, through specifically targeting its 3’UTR, leading to decreased tumor cell clonogenicity and induced apoptosis." (PMID 41170181, 2025). "These include the overexpression of PLK1, AURKB, BIRC5 (survivin, 1.23 log2FC), and certain CENP isoforms, suggesting that HS tumor cells undergo unrestrained mitosis." (PMID 40149290, 2025). "Its overexpression in various tumor types enhances cell proliferation by modulating mitotic regulators such as protein phosphatase 1 (PP1), polo-like kinase 1 (PLK1), targeting protein for XKLP2 (TPX2), and large tumor suppressor 1/2 (LAST1/2)." (PMID 40722776, 2025). "However, Plk1 protein was still detectable in tumors derived from Plk1-depleted mice, suggesting the incomplete Plk1 depletion due to leaky Cre recombinase activity may have contributed to sustained tumor growth." (PMID 41284701, 2025). "Of particular note, PLK1 and UHRF1 emerged as potential oncogenic hubs, reaffirming their roles in both tumour proliferation and ferroptotic resistance." (PMID 41007424, 2025). "It has been reported that due to the inhibition of PLK1 and mitochondrial dysfunction, the apoptosis rate of HCC cells increases, and a synergistic anti‐tumor effect can be observed both in vitro and in vivo." (PMID 39823156, 2025). "Non-ATPcompetitive inhibitors, such as Rigosertib, which targets the PBD and inhibits both PLK1 and PI3K, have shown efficacy in killing tumor cells in vitro and in vivo." (PMID 40612941, 2025). "Specifically, TFRC, PLK1, TYMS, and TSSK6 were remarkably upregulated in tumor tissues compared to normal controls (P < 0.0001)." (PMID 40496862, 2025). "If PLK1/PRC1 signaling is blocked, tumor growth is inhibited, and drug-resistant tumors become more sensitive to conventional chemotherapy." (PMID 40612941, 2025). "There was a notable positive correlation between the expression of PLK1 and the expression of proliferating cell nuclear antigen (PCNA) (R = 0.68) in tumor tissue (right)." (PMID 40355412, 2025). "PLK1 expression can promote MYC to activate Hedgehog signaling pathway by degrading PDCD4, and then promote the proliferation of tumor cells." (PMID 40612941, 2025). "PLK1-specific CD4(+) and CD8(+) T cells can be induced by mPLK1 RNA/DC vaccine and exert anti-tumor effects." (PMID 40612941, 2025). "On the basis of the proven tumor-promoting effect of TRIM47, a PLK1 plasmid was transfected into TRIM47-knockdown LC cell lines to counteract the retardation of proliferation caused by TRIM47 interference." (PMID 41460629, 2025). "Tumor tissues exhibited significant upregulation of CDCA8, AURKA, and PLK1, whereas NR3C2 was notably downregulated (p < 0.0001)." (PMID 41357242, 2025). "Because inhibition of PLK1 can induce the up-regulation of PD-L1 through the MAPK pathway and enhance the sensitivity of tumor cells to immune checkpoint inhibitors." (PMID 40612941, 2025). "A heatmap analysis was conducted using a TCGA dataset of LUAD patients for TNFAIP6, PLK1, and mesenchymal markers including CDH2, SNAI1, and SNAI2 in paired normal tissue (left, normal) and adjacent tumor tissues (right, LUAD) depending on stages." (PMID 40860188, 2025). "Transcriptional analysis showed a marked downregulation of key genes involved in tumor cell growth and proliferation, including CDK1, CDK2, and CDK6 (up to a 31.11‐fold decrease), PLK1 (up to a 21.49‐fold decrease), and SKP2 (up to a 14.68‐fold decrease)." (PMID 41221154, 2025). "In order to assess tumor target occupancy, BAL0891-unoccupied TTK and PLK1 were evaluated in tumors obtained from treated mice." (PMID 39184047, 2024). "This suggests a tumor-suppressive role for PLK2, found to be mediated by a direct interaction of PLK2 with PLK1, whose overexpression is involved in TNBC growth." (PMID 38473804, 2024).
tumor (continued). "This suggests that PLK1 contributes to chemoresistance through the induction of CSC characteristics, potentially leading to tumor persistence and relapse." (PMID 39451218, 2024). "In this study, we identified the upregulation of PLK1 and MISP in CCA patient tumor tissues and further uncovered the mechanism by which PLK1 and MISP mediate lymphatic invasion in iCCA." (PMID 38057358, 2024). "We found that the down-regulated miR-5100 target genes (PLK1, CCNB1, CDKN2A) were significantly upregulated, indicating their tumor-promoting effect in PCa." (PMID 39590378, 2024). "The combined treatment of a PLK1 inhibitor (volasertib) and a FoxM1 inhibitor (thiostrepton) demonstrated a synergistic effect in reducing PTC cell growth in vitro and delaying tumor growth in vivo." (PMID 38361222, 2024). "The mRNA expression of SPIB, PLK1, and CD24 is upregulated in clinical tumor tissues, whereas NTRK3 and EDA2R mRNA expression is downregulated." (PMID 39596658, 2024). "In this study, we revealed the potential tumor-inhibitory properties of UDCA and suggested a plausible potential tumor inhibition strategy involving the combination of UDCA with PLK1 inhibitors." (PMID 38255993, 2024). "Heatmap analysis of cell cycle gene expression showed increased expression of PLK1 (polo-like kinase 1) and its substrate MISP (mitotic spindle positioning) in iCCA tumor samples." (PMID 38057358, 2024). "Under high PLK1 condition, TME is characterized by low tumor infiltrating lymphocytes and high secreted CXCL2, which promotes M2 polarization and disrupts antigen processing and presentation." (PMID 38885192, 2024). "Increased expression of PLK1 and MISP correlated with higher risks of tumor number, N stage, and lymphatic invasion in late-stage iCCA patients and with poor prognosis." (PMID 38057358, 2024). "The ATAC-seq tracks from the genome datasets showed high chromatin-accessible regions in the promoters of PLK1 and MISP in tumor tissues, consistent with the ATAC-seq analysis." (PMID 38057358, 2024). "Increased expression of PLK1 and MISP was significantly correlated with tumor number, N stage, and lymphatic invasion in an iCCA cohort." (PMID 38057358, 2024). "Hub genes, including PLK1, CDK1, and EGFR, emerged as critical regulators of tumor proliferation and immune responses." (PMID 39457373, 2024). "Overexpression and dysregulation of several mitotic regulators, including the SAC kinases Threonine Tyrosine Kinase (TTK) and Polo-Like Kinase 1 (PLK1), are mechanisms through which tumor cells can tolerate high aneuploidy and CIN." (PMID 39184047, 2024). "Analysis of the GSE159115 database showed that five genes in malignant and stromal cells differed significantly between tumour and normal tissues, but only MXD3, NUF2 and PLK1 in immune cells." (PMID 38546385, 2024). "It is highly likely, based on the novel MoA of BAL0891 and the discussion above, that tumor response biomarkers will differ from those postulated for TTK- and PLK1-specific compounds." (PMID 39184047, 2024). "We further confirmed the mRNA expression of PLK1 and MISP in five iCCA tumor samples and their adjacent normal liver tissues." (PMID 38057358, 2024). "TKM-PLK1 specifically targets polo-like kinase 1 (PLK1), a protein critical in driving tumor cell proliferation and recognized as a validated target within oncology." (PMID 38276502, 2024). "Key hub genes, such as PLK1, CDK1, and EGFR, emerge as crucial regulators of tumor proliferation, signal transduction, and immune response." (PMID 39457373, 2024). "Our findings here demonstrated that LAS exerts anti-tumor effects by inhibiting PLK1/CDC25C and PLK1/AKT pathways." (PMID 38495493, 2024). "Under low PLK1 condition, TME is characterized by a higher proportion of tumor infiltrating lymphocytes and a lower level of CXCL2, and this condition is associated with more M1 polarization and functional antigen presentation pathway." (PMID 38885192, 2024).